RPS6KA3 (ribosomal protein S6 kinase A3)
Description:
Serine/threonine-protein kinase that acts downstream of ERK (MAPK1/ERK2 and MAPK3/ERK1) signaling and mediates mitogenic and stress-induced activation of the transcription factors CREB1, ETV1/ER81 and NR4A1/NUR77, regulates translation through RPS6 and EIF4B phosphorylation, and mediates cellular proliferation, survival, and differentiation by modulating mTOR signaling and repressing pro-apoptotic function of BAD and DAPK1. In fibroblast, is required for EGF-stimulated phosphorylation of CREB1 and histone H3 at 'Ser-10', which results in the subsequent transcriptional activation of several immediate-early genes. In response to mitogenic stimulation (EGF and PMA), phosphorylates and activates NR4A1/NUR77 and ETV1/ER81 transcription factors and the cofactor CREBBP. Upon insulin-derived signal, acts indirectly on the transcription regulation of several genes by phosphorylating GSK3B at 'Ser-9' and inhibiting its activity. Phosphorylates RPS6 in response to serum or EGF via an mTOR-independent mechanism and promotes translation initiation by facilitating assembly of the preinitiation complex. In response to insulin, phosphorylates EIF4B, enhancing EIF4B affinity for the EIF3 complex and stimulating cap-dependent translation. Is involved in the mTOR nutrient-sensing pathway by directly phosphorylating TSC2 at 'Ser-1798', which potently inhibits TSC2 ability to suppress mTOR signaling, and mediates phosphorylation of RPTOR, which regulates mTORC1 activity and may promote rapamycin-sensitive signaling independently of the PI3K/AKT pathway. Mediates cell survival by phosphorylating the pro-apoptotic proteins BAD and DAPK1 and suppressing their pro-apoptotic function. Promotes the survival of hepatic stellate cells by phosphorylating CEBPB in response to the hepatotoxin carbon tetrachloride (CCl4). Is involved in cell cycle regulation by phosphorylating the CDK inhibitor CDKN1B, which promotes CDKN1B association with 14-3-3 proteins and prevents its translocation to the nucleus and inhibition of G1 progression (By similarity). In LPS-stimulated dendritic cells, is involved in TLR4-induced macropinocytosis, and in myeloma cells, acts as effector of FGFR3-mediated transformation signaling, after direct phosphorylation at Tyr-529 by FGFR3 (By similarity). Negatively regulates EGF-induced MAPK1/3 phosphorylation via phosphorylation of SOS1 (By similarity). Phosphorylates SOS1 at 'Ser-1134' and 'Ser-1161' that create YWHAB and YWHAE binding sites and which contribute to the negative regulation of MAPK1/3 phosphorylation (By similarity). Phosphorylates EPHA2 at 'Ser-897', the RPS6KA-EPHA2 signaling pathway controls cell migration. Acts as a regulator of osteoblast differentiation by mediating phosphorylation of ATF4, thereby promoting ATF4 transactivation activity (By similarity).
Synonyms: ISPK-1; MAPKAPK1B; RSK2; HU-3; CLS; MRX19; RSK; S6K-alpha3; XLID19; p90-RSK2; pp90RSK2
Tractability: Small molecule: a drug acting on it is in phase 1 trials; a structure with a bound ligand is known; a high-quality ligand is known; it belongs to a druggable protein family. PROTAC: it is named in the literature on targeted protein degradation; ubiquitination databases record sites on it; its protein half-life has been measured; a small molecule that binds it is known.
Target class: Enzyme; Kinase; AGC protein kinase group; AGC protein kinase RSK subfamily; Protein Kinase; AGC protein kinase RSK family
Chemical probes: BI-D1870, BI00645435 (high quality), CHEMBL1933279
Safety:
Unwanted effects reported when the protein is acted on. In parentheses: how it was acted on, where the effect was seen, and who reports it.
cardiac arrhythmia (cardiovascular system; source: Lamore et al. (2017))
Gene: Protein-coding gene on chromosome X (20,149,911 to 20,267,519, reverse strand). Ensembl gene ENSG00000177189.
Subcellular location: Nucleus; Cytoplasm
Subcellular location (Human Protein Atlas): Nucleoplasm; Cytosol; Nucleoli; Vesicles
Pathways (Reactome):
Signal Transduction: CREB phosphorylation; ERK/MAPK targets; Gastrin-CREB signalling pathway via PKC and MAPK
Neuronal System: CREB1 phosphorylation through NMDA receptor-mediated activation of RAS signaling; RSK activation
Cellular responses to stimuli: Senescence-Associated Secretory Phenotype (SASP)
Developmental Biology: Recycling pathway of L1
Gene Ontology:
Molecular function: protein binding; protein serine kinase activity; protein kinase activity; protein serine/threonine kinase activity; ribosomal protein S6 kinase activity; ATP binding; magnesium ion binding; protein kinase binding
Biological process: negative regulation of apoptotic process; positive regulation of transcription by RNA polymerase II; central nervous system development; chemical synaptic transmission; positive regulation of cell differentiation; positive regulation of cell growth; regulation of DNA-templated transcription; regulation of translation in response to stress; response to lipopolysaccharide; signal transduction; skeletal system development; toll-like receptor signaling pathway; TORC1 signaling; intracellular signal transduction
Cellular component: cytoplasm; cytosol; nucleolus; nucleoplasm; nucleus; synapse
Gene-disease validity (ClinGen):
ClinGen rates the evidence that RPS6KA3 causes each of these diseases.
Coffin-Lowry syndrome (X-linked): Definitive. A rare X-linked syndromic intellectual disability characterized by global development delay, postnatal growth retardation leading to short stature, facial dysmorphism, short hands with tapering fingers and progressive skeletal abnormalities including kyphoscoliosis and pectus carinatum/excavatum.
Homologues: Orthologues: chimpanzee RPS6KA3 (100% identical), dog RPS6KA3 (99% identical), mouse Rps6ka3 (99% identical), pig RPS6KA3 (99% identical), guinea pig RPS6KA3 (99% identical), rat Rps6ka3 (97% identical), rabbit RPS6KA3 (97% identical), macaque RPS6KA3 (96% identical), tropical clawed frog rps6ka3 (93% identical), zebrafish rps6ka3a (85% identical), zebrafish rps6ka3b (82% identical), Caenorhabditis elegans rskn-2 (36% identical), and 5 more. Paralogues in human: RPS6KA2 (80% identical), RPS6KA1 (79% identical), RPS6KA6 (77% identical), RPS6KA5 (44% identical), RPS6KA4 (41% identical), RPS6KB1 (30% identical), RPS6KB2 (28% identical).